ABCC3 (ATP binding cassette subfamily C member 3)
Diseases named in the same sentence as ABCC3 in open-access papers (continued):
Sharing a sentence is not in itself a finding about the gene and the disease.
cancer (continued). "ABCC3 is a member of the MRP subfamily which is involved in multi-drug resistance to chemotherapeutic agents, playing a major role in the failure of cancer therapy." (PMID 24625834, 2014). "Twenty of these genes are located in 8q22–q24 and 17q21, including PAPBC1, RAD21, ATAD2, MTSS1, SQLE, ST3GAL1, C17orf37, ABCC3 and PTPN2, previously reported as cancer-related genes." (PMID 21339811, 2011). "The identification of many well-defined cancer gene markers (representing oncogenes), such as EGFR, osteopontin (SPP1), ERBB3, MALAT1, S100A2, S100A6, ABCC3 and ELN3, as highly discriminative genes by the ECD is quite encouraging." (PMID 22369099, 2011). "Variants in ABC transporter genes, including ABCB1, ABCC4, and ABCC3, as well as solute carrier (SLC) genes such as SLC28A3, are known to influence the pharmacokinetics of numerous anti-cancer agents, including fluoropyrimidines, methotrexate, anthracyclines, and irinotecan." (PMID 40428413, 2025). "Moreover, gene expression of some transporters (ABCC1, ABCC2, ABCC3, and ABCB3) was significantly elevated in recurrent cancer lesions compared with benign or malignant ovarian tissue." (PMID 35164068, 2022). "Notably ABCC3 is part of the ABC subfamily of multidrug resistance proteins, known to be a major detriment to cancer therapy." (PMID 33947409, 2021). "Thus, ABCC3 protein and the SNP −897DelC can play a predictive role in patients affected by GBM, and possibly other cancers, treated with dendritic cell immunotherapy combined with chemotherapy." (PMID 31771235, 2019). "ABCC3 conferred resistance to methotrexate in other cancers; however, whether or not rs4148416 can influence the activity of the ABCC3 protein has to our knowledge not been demonstrated so far." (PMID 34572110, 2021). "Some selected genes with high discriminative ability, belonging to three cancer-relevant pathways, such as ATP-binding cassette (ABC) family of genes (ABCA4, ABCA8) were identified as prospective gene markers of lung AC other one (ABCB1, ABCC3 and ABCF2) should be also under serious consideration." (PMID 22369099, 2011). "The demonstration of a predictive role of ABCC3 expression in NK cells, if confirmed on a larger number of patients, may have a relevant impact on selecting patients affected by GBM, and possibly other cancers, likely to obtain clinical benefit from chemoimmunotherapy." (PMID 31771235, 2019).
tumor (77 papers, 1995 to 2025). "High ABCC3 gene expression was associated with stronger tumor response in group 2 as well as a strong association with better PFS." (PMID 40357991, 2025). "Multivariate linear regression analysis identified SNPs in 11 genes (Sepsecs, Rhobtb1, Tsen15, Abcc3, Arid5b, Tnr, Dock2, Tti1, Fam81a, Stx6, and Oxr1) that were independently associated with the tumour multiplicities." (PMID 39067134, 2024). "We pooled all 20 genes (Stx6, Ramp1, Traf3ip1, Nckap5, Pfkfb2, Trmt1l, Rprd1b, Rer1, Sepsecs, Rhobtb1, Tsen15, Abcc3, Arid5b, Tnr, Dock2, Tti1, Fam81a, Oxr1, Plxna2 and Tbc1d31) together as the mouse tumour susceptibility gene signature (mTSGS)." (PMID 39067134, 2024). "ABCC3 is a member of the ATP-binding cassette transporter superfamily, it is strongly associated with tumor drug resistance, leading to chemotherapy failure." (PMID 37334354, 2023). "Thus, the effects of ABCC3 downregulation on both epithelial tumour cells and associated fibroblast may be assessed in this cell line." (PMID 31378204, 2019). "Central to this resistance mechanism are ATP-binding cassette (ABC) transporters, with ABCC3 (MRP3) emerging as a critical mediator of chemotherapeutic drug efflux and tumor progression." (PMID 40427480, 2025). "For group 2, it included ECOG performance status, ABCC3 expression, tumor differentiation, percentage of tumor epithelial cells in specimen, PCFT expression, and MTHFD2 expression." (PMID 40357991, 2025). "Depending on tumor location, the expression of ABCC3, AMT, GGH, and RFC-1 in mucosa, as well as the tumoral expression of AMT, GGH, PCFT and RFC-1 differed." (PMID 39998667, 2025). "Another common contributor to chemoresistance is the upregulation of the ABC transporters, like ABCC3, whose role is to export drugs out of the tumor cells via transmembrane ATP pumps." (PMID 40385549, 2025). "In agreement with previous studies on chemotherapy-naïve stage I–IV CRC, tumor tissue exhibited significantly lower expression of ABCC3 compared to mucosa." (PMID 39998667, 2025). "High ABCC3 expression and low TYMS expression were significantly associated with better tumor response across the entire study cohort (p = 0.023 and p = 0.0009, respectively)." (PMID 40357991, 2025). "Previous studies have demonstrated that ABCC3 contributes critically to drug resistance across various tumor types." (PMID 41304944, 2025). "In particular, ABCC3 (MRP3) represents a compelling target due to its established role in drug efflux and tumor progression." (PMID 40427480, 2025). "In group 2, high ABCC3 and low TYMS expression were associated with improved tumor response (p = 0.036 and p = 0.018, respectively)." (PMID 40357991, 2025). "ABCC3, in turn, can alter the tumor microenvironment to induce drug resistance and promote tumor proliferation." (PMID 38291517, 2024). "The capacity of NbA42 and NbA213 to target ABCC3 in vivo was evaluated in xenografted tumor-bearing mice of the A549 and A549ABCC3KO control cell lines." (PMID 36585418, 2022). "Circ-ABCC3 acts as a sponge for miR-770-5p, which targets SOX2, and knockdown of Circ-ABCC3 significantly inhibits tumor growth in vivo." (PMID 34881248, 2021). "The mRNA level of the ABCC3 gene was elevated in tumor samples before the chemotherapeutic treatment, while this effect disappeared after the treatment." (PMID 35008510, 2021). "More importantly, tumour growth in a xenograft mouse model was remarkably affected by the presence of active ABCC3." (PMID 31378204, 2019). "We have recently demonstrated that ABCC3 plays a prominent role in stimulating PDAC cell and tumour growth, suggesting the potential of ABCC3 as a novel target in PDAC therapy." (PMID 31378204, 2019). "Consistent with a reduction in the stem-like cell population in vitro, knockdown of ABCC3 reduced the tumor formation ability in-vivo." (PMID 27171227, 2016).
tumor (continued). "The combined effect of ABCC3 depletion and doxorubicin treatment led to greater tumor growth retardation than individual treatments." (PMID 27171227, 2016). "Tumor burden was increased in ABCC3 knock-out mice, as carcinoma developed earlier and their incidence was higher than in control littermates." (PMID 26501075, 2015). "To understand the mechanism giving ABCC3 these tumor suppressive properties, we investigated its transport function." (PMID 26501075, 2015). "ABCC3 might regulate reduced folate levels in tumor tissue after LV administration by extruding specific folate metabolites, and seems to have a preference for 10‐formyltetrahydrofolate." (PMID 40357991, 2025). "It is also possible that ABCC3 exports folates to surrounding tumor cells which could be advantageous during treatment with 5‐FU in combination with LV or other folates." (PMID 40357991, 2025). "Further protein analysis via Western blotting revealed that the expression of CAV-1, ABCB1, and ABCC3 proteins in tumor tissues was significantly downregulated in the PPH + PTX group, with the degree of inhibition stronger than that observed in the lovastatin + PTX group." (PMID 41304944, 2025). "Furthermore, ABCB1-p-glycoprotein (p = 0.008) and ABCC3 (p = 0.020) exhibited a significant downregulation in the COS tumour tissues when compared to the healthy donors." (PMID 39335211, 2024). "Multivariate analyses flagged SNPs in 20 genes (Stx6, Ramp1, Traf3ip1, Nckap5, Pfkfb2, Trmt1l, Rprd1b, Rer1, Sepsecs, Rhobtb1, Tsen15, Abcc3, Arid5b, Tnr, Dock2, Tti1, Fam81a, Oxr1, Plxna2, and Tbc1d31) independently tied to various tumour characteristics, designated as a mTSGS." (PMID 39067134, 2024). "Analysis of tumour tissues dissected from the KPC mice also demonstrated overexpression of ABCC3." (PMID 31378204, 2019). "Furthermore, high expression of ABCC3 and ABCC5 in tumor biopsy samples is linked to a higher risk of death." (PMID 25605243, 2015). "At least ABCC3 is normally considered to be epithelial; however, stromal cells participating in tumor progression may enrich ABCC3 which could explain the lack of correlation between ABCC3 expression and percentage of tumor epithelial cells in group 2." (PMID 40357991, 2025). "Additionally, circ-ABCC3 silencing inhibited tumor growth in vivo." (PMID 35883576, 2022). "Similarly, genetic knockdown of ABCC3 and treatment of the primary cell line with MCI-715 reduced the expression levels of α-SMA and vimentin, in agreement with the hypothesis that ABCC3 is involved in both PDAC tumour and stroma development." (PMID 31378204, 2019). "In contrast, mRNA expressions of ABCC3 (MRP3) and ABCG2 are induced, which may be important for the efficacy of chemotherapeutics when these drugs’ intestinal absorption (assuming oral administration) or transport out of the tumor cell is modulated by MRP3 or BCRP, respectively." (PMID 25521244, 2014). "ABCC3, RFC‐1, PCFT, MFT, MTHFD2, and TYMS expression was determined by qPCR and related to tumor response and 3‐year progression‐free survival (PFS)." (PMID 40357991, 2025). "The percentage of tumor epithelial cells in specimens correlated positively with RFC‐1 expression and with ABCC3 expression in group 1, indicating that these genes are either epithelial‐specific or not highly expressed in stromal cells." (PMID 40357991, 2025). "The multivariable analysis further underscored the significance of age, ABCC3, ERCC1, RFC1, and specific tumour histologies in predicting treatment outcomes." (PMID 39335211, 2024). "Subsequently, we compared the mRNA level of ABCC3, CPS1, and TRIP6 genes in EOC tumor samples with control ovarian tissues." (PMID 35008510, 2021).
tumor (continued). "Circ-ABCC3 regulates GBM angiogenesis and tumor malignancy progression through PI3K/AKT signaling pathway and miR-770-5p/SOX2 axis." (PMID 34881248, 2021). "From a long-running medicinal chemistry/drug discovery process, we identified a novel small-molecule inhibitor of ABCC3, which reduces PDAC progression in vitro and tumour growth and disease progression in vivo in several animal models." (PMID 31378204, 2019). "High ABCC3 expression was observed not only in the tumour ducts, but also in the stroma of KPC mice tissue samples, suggesting a potential role of ABCC3 in the tumour microenvironment." (PMID 31378204, 2019). "ABCC3-mediated regulation of PDAC cell proliferation and tumour growth in vivo was demonstrated and was shown to be conferred by upregulation of STAT3 signalling and regulation of apoptosis." (PMID 31378204, 2019). "Further, it was reported that expression levels of ABCC3 and ABCC5 changed during tumor development, and the expression of ABCC3 was significantly correlated with high tumor grade." (PMID 31622355, 2019). "We have recently reported that downregulation of ABCC3 with the use of a specific shRNA decreased PDAC cell growth in vitro and importantly, significantly reduced tumour growth in a xenograft mouse model." (PMID 31378204, 2019). "The results of the study showed that tumour tissue of untreated patients had higher expression of FPGS, GGH, MTHFD1L, and SLC19A1/RFC-1 compared with mucosa, whereas expression of ABCC3/MRP3 and SLC46A1/PCFT was higher in mucosa compared with tumour." (PMID 30269276, 2018). "We analyzed for expression of five ABC transporters ABCB1, ABCC1, ABCC2, ABCC3 and ABCG2 using immunohistochemistry in 103 pre-treatment tumor specimens obtained from patients with CHL." (PMID 22871336, 2012). "Additionally, increasing doses of LV influence folate‐related gene expression, and there seems to be a correlation between the expression of the genes ABCC3, PCFT, and RFC‐1 and folate concentrations in tumor tissue." (PMID 40357991, 2025). "The aim of the present study was to assess the association between primary tumor expression of six selected folate pathway genes, ABCC3, RFC‐1, PCFT, MFT, MTHFD2, and TYMS, and tumor response as well as 3‐year progression‐free survival (PFS) of patients with mCRC." (PMID 40357991, 2025). "Furthermore, the mRNA expression levels of ABCC3 (p = 0.020) and ABCB1, also known as p-glycoprotein (p = 0.008), exhibited a significant downregulation in the tumour tissues of COS patients tumour when compared to the healthy donors." (PMID 39335211, 2024). "Furthermore, the tumour tissues with histologically confirmed COS exhibited a significant downregulation in their mRNA expression profiles for ABCB1 (p-glycoprotein) and ABCC3 compared to the healthy donor muscles, as measured using real-time PCR." (PMID 39335211, 2024). "Moreover, metastasis presented higher ABCC1, ABCC3 and ABCC4 expression and lower SLC22A1 and ABCC10 expression than the primary tumor." (PMID 36982681, 2023). "Human tumor transcriptomic data for 377 HCC patients also show a positive correlation of multiple ABC transporters including the ABCB1, ABCC3, ABCC9 and ABCG2 with GHR expression, while ABCC1,ABCC4 and ABCG1 levels correlated with IGF1R expression, confirming our in vivo observations." (PMID 35865483, 2022).
tumor (continued). "Based on our findings, we speculate that the remarkable effects observed in animal models of PDAC after ABCC3 pharmacological modulation are due in part to the indirect inhibition of STAT3 pathway and hypoxia both in the tumour and surrounding stroma." (PMID 31378204, 2019). "Importantly, we show that ABCC3 inhibition not only affects PDAC tumours, but also targets PDAC stroma, which is enriched in ABCC3." (PMID 31378204, 2019). "ABCC3, a member of the ATP-binding cassette (ABC) transporter family, is known for its role in drug resistance in many types of tumors, including GBM, where it is overexpressed and correlates with tumor progression, worse prognosis, and a lower response to TMZ." (PMID 40427760, 2025). "The expression of ABCC3, AMT and PCFT (p < 0.0001) was higher in mucosa compared to the tumor tissue, whereas the expression of FPGS (p < 0.0001), GGH (p < 0.0001), MFT (p < 0.01), RFC-1 (p < 0.0001) and TYMS (p < 0.0001) was lower in mucosa compared to the tumor tissue." (PMID 39998667, 2025). "Genes involved in drug resistance, ABCC3 and metallothioneins, which could play a role in drug resistance, were highly expressed in Patient 2’s tumor tissue, explaining his non-responsiveness to chemotherapy." (PMID 19830138, 2009). "There were no significant changes in expression between the tumor and control tissues in the ABCB4, ABCA13, ABCC2, ABCC3, and ABCG2 genes." (PMID 36674773, 2023). "However, this was not the case for ABCC3/MRP3 and SLC46A1/PCFT, which consistently had higher expression levels in mucosa, compared to tumour in each of the treatment groups." (PMID 30269276, 2018). "However, this was not the case for ABCC3/MRP3 and SLC46A1/PCFTPCFT, which had higher expression levels in mucosa compared to tumour." (PMID 30269276, 2018).
infection (7 papers, 2013 to 2025). The state of being infected such as from the introduction of a foreign agent such as serum, vaccine, antigenic substance or organism. "To validate findings in this present study of productive infection, we examined all quantified ABC transporters and found selective downregulation of ABCC1 as well as ABCC3." (PMID 24906157, 2014).
adenocarcinoma (2 papers, 1995 to 2014). A common cancer characterized by the presence of malignant glandular cells. "In our study, we found that ABCC3 expression was higher in adenocarcinoma than in SCC and found that the expression of this gene may be regulated by miRNA-149." (PMID 24625834, 2014).
metabolic disorders (1 paper, 2021). "However, total BAs, and Abcc3, Abcc11, Cyp7a1 mRNA levels were unchanged in this study, suggesting that there might be a dynamic equilibrium of total BAs in GUDCA-alleviated diet-induced metabolic disorders." (PMID 34236076, 2021).
ABCC3 also shares sentences with these, for which no sentence is quoted: gastric cancer (4 papers); liver disease (3); liver fibrosis (3); acute myeloid leukemia (2); anaplastic astrocytoma (2); astrocytoma (2); Cholestatic liver disease (2); diabetes (2); hepatic cancer (2); invasive breast ductal carcinoma (2); squamous cell carcinoma (2); transitional cell carcinoma of the bladder (2); acute coronary syndrome (1); benign tumors (1); cholangiocarcinoma (1); Cirrhosis (1); colitis (1); colonic adenocarcinoma (1); coronary heart disease (1); cyst (1); depression (1); endometriosis (1); endotoxemia (1); esophageal (1); esophageal tumor (1); Fusarium infection (1); glaucoma (1); gynecological disease (1); Hepatic steatosis (1); hepatitis C (1).
A further 30 diseases each share a sentence with ABCC3 in 1 paper.